BNC1 (basonuclin zinc finger protein 1)
Diseases named in the same sentence as BNC1 in open-access papers (continued):
Sharing a sentence is not in itself a finding about the gene and the disease.
melanoma (1 paper, 2017). A malignant, usually aggressive tumor composed of atypical, neoplastic melanocytes. "LINC00888 is negatively correlated with BNC1, which implies a potentially active role in melanoma." (PMID 28225791, 2017).
mesothelioma (1 paper, 2020). A usually malignant and aggressive neoplasm of the mesothelium which is often associated with exposure to asbestos. "The study found that Epigenetic alterations occurred in the BNC1 gene in the mesothelioma cell line and may be involved in mesothelioma progression." (PMID 33166290, 2020).
metastatic tumours (1 paper, 2015). "This suggests differing roles for these genes in the evolution of metastatic tumours; CCDC8 methylation occurs at an early stage of metastatic evolution whereas methylation of GANLT9 and BNC1 occurs at a later stage of tumour evolution." (PMID 26052355, 2015).
premature ovarian failure (1 paper, 2021). "Specifically, BNC1 is expressed in oocytes present within secondary follicles and in ovulated oocytes and its deficiency has been associated with premature ovarian failure." (PMID 33908703, 2021).
squamous cell carcinoma (1 paper, 2014). A carcinoma arising from squamous epithelial cells. "A recent publication demonstrated BNC1 to be a direct transcriptional target for the tumor suppressor gene p63, thus its loss could affect the tumor suppressing effect of p63, but in this publication the expression of BNC1 and p63 were elevated in the squamous cell carcinomas that were studied." (PMID 24454902, 2014).
tumor (14 papers, 2008 to 2025). "BNC1 encodes a transcription factor that is important in the regulation of keratinocyte differentiation and why the loss this transcription factor would be advantageous to tumor growth or progression is yet to be elucidated." (PMID 24454902, 2014). "Subcutaneous tumor model experiments were carried out, and the results showed that, after overexpressing BNC1, tumor volume and tumor weight were significantly reduced and the nuclear-cytoplasmic ratio of tumors was also significantly reduced." (PMID 40444282, 2025). "Conversely, studies have documented reduced expression of BNC1 in renal cell carcinoma and hepatocellular carcinoma, implying a potential tumor suppressor function." (PMID 40444282, 2025). "Further functional assays, both in vitro and in vivo, demonstrated that BNC1 overexpression inhibited tumor cell proliferation and metastasis." (PMID 40444282, 2025). "BNC1 gene had significantly higher methylation frequency among IPMN-related advanced neoplasia compared to IPMN-LGD (66% vs. 3%, P < 0.001)." (PMID 36803844, 2023). "We demonstrated that highly specific methylation markers in BNC1/CACNA1G genes can be utilized to differentiate IPMN with advanced neoplasia from LGD lesions." (PMID 36803844, 2023). "A study published in 2019 showed that the methylation status of ADAMTS1 and BNC1 in cell-free DNA is highly sensitive and specific to the early diagnosis of PC, these epidemiological markers varying with tumor stage." (PMID 33114412, 2020). "Methylation of ADAMTS1 and BNC1 showed a certain sensitivity and specificity for the early diagnosis of this neoplasia." (PMID 33114412, 2020). "The frequency and intensity of BNC1 promoter hypermethylation in tumor tissues was significantly higher than that in adjacent non-tumor tissues." (PMID 26821013, 2016). "But the BNC1 promoter hypermethylation intensity in tumor tissues with different infection backgrounds was higher than that in each group of corresponding non-tumor tissues." (PMID 26821013, 2016). "Five genes (BNC1, COL14A1, CST6, PDLIM4, and SFRP1) demonstrated frequent tumor-specific promoter region methylation (>30%), associated with transcriptional silencing." (PMID 28326264, 2015). "By Cox proportional-hazards regression, two probes were statistically significant indicators, but were both less significant than tumor grade; BNC1 (p = 0.050, HR = 1.76, CI = 1.00–3.08) and ZSCAN18 (p = 0.028, HR = 1.87, CI = 1.07–3.24)." (PMID 24454902, 2014). "Accumulating evidence indicates that BNC1 plays a significant role in tumor development." (PMID 40444282, 2025). "The low frequency of methylation in primary tumours indicates that BNC1 and CCDC8 may contribute to BBM and are good candidates for further investigation." (PMID 26052355, 2015). "To ensure that CoBRA digests were representative of high methylation status in tumours, we carried out base-resolution analysis of promoter region methylation for BNC1, CCDC8 and GALNT9 by cloning and sequencing individual bisulfite-modified alleles from select tumours." (PMID 26052355, 2015). "The previous study in RCC also associated BNC1 hypermethylation with poorer patient prognosis independent of tumor stage, grade or dimension." (PMID 24454902, 2014). "Thus, BNC1 was thought to be a potential tumor suppressor gene in these tumors." (PMID 26821013, 2016). "We also identified genes encoding membrane receptors (IL7R, OSMR, EGFR) and transcriptional regulators (BNC2, BNC1, HMGA2, KLF7, NR3C1) as enriched in Basal tumours." (PMID 36944729, 2023). "This study investigates our DNA methylation-based PC biomarker panel (ADAMTS1, BNC1, and CACNA1G genes) in differentiating IPMN-advanced neoplasia from IPMN-LGDs." (PMID 36803844, 2023). "As compared to IPMN-LGDs, IPMN-advanced neoplasia had higher hypermethylation frequency of candidate genes: ADAMTS1 (60% vs. 14%), BNC1 (66% vs. 3%), and CACGNA1G (25% vs. 0%)." (PMID 36803844, 2023).
tumor (continued). "In this study, the expression levels and methylation statuses of BNC1 and BNC2 were investigated in primary HCC tissues and their corresponding adjacent non-tumor liver tissues, in order to investigate the potential roles of BNC1 and BNC2 genes in HCC." (PMID 26821013, 2016). "Numerous lines of investigation have demonstrated that the aberrant expression of BNC1 and BNC2 contribute to tumor progression." (PMID 26821013, 2016). "Because of the higher frequency of the BNC1 methylation detected in HCC cell lines, we then tested the methylation status of BNC1 in tumor and adjacent non-tumor tissues derived from 127 primary HCC patients and 10 normal liver tissues." (PMID 26821013, 2016). "Re-expression of BNC1, CST6, and SFRP1 suppressed the growth of RCC cell lines, whereas RNAi knock-down of BNC1, SFRP1, and COL14A1 increased their growth, suggesting tumor suppressor activity." (PMID 28326264, 2015). "BNC1, CCDC8 and GALNT9 were frequently downregulated or silenced in these tumours and reduced expression correlated to promoter methylation as determined by CoBRA and base-resolution sequencing." (PMID 26052355, 2015). "With threshold value of methylation intensity set at 10%, the high frequency of BNC1 hypermethylation was found in tumor tissues (49.6%, 63/127), but not in the adjacent non-tumor tissues (3/127, 2.36%)." (PMID 26821013, 2016). "Since BNC1 was silenced by hypermethylation in HCC, functional assays should be performed in vitro and in vivo to investigate whether BNC1 also exhibits anti-tumor function in the development of HCC in the future." (PMID 26821013, 2016). "Moreover, we have shown that BNC1 promoter methylation is a late event in tumour evolution, only occurring in the brain metastasis of a BBM patient and not in the associated primary tumour." (PMID 26052355, 2015). "Next, we tested the expression levels of BNC1 and BNC2 in 30 pairs of matched tumor and their adjacent non-tumor tissues." (PMID 26821013, 2016).
cancer (8 papers, 2016 to 2025). A tumor composed of atypical neoplastic, often pleomorphic cells that invade other tissues. "BNC1 expression was predominantly nuclear and was significantly lower in cancer tissues compared to adjacent normal tissues." (PMID 40444282, 2025). "Overall methylation of either gene (ADAMTS1 and/or BNC1) was observed in 97.4% of cancer patients (38/39) compared to 8.4% of control patients (8/95)." (PMID 30953539, 2019). "We now show that a two-gene methylation panel (ADAMTS1 and/or BNC1) demonstrated significant improvement in the detection rate, showing an even higher rate of positivity in stage I and stage II cancers (100% and 94.4%, respectively)." (PMID 30953539, 2019). "In recent years, the role of BNC1 in cancer has garnered increased attention." (PMID 40444282, 2025). "Also, the methylation of BNC1 was positive in 62.5% of patients with stage I cancers, 55.6% of patients with stage IIA, 65% of patients with stage IIB, and 100% of patients with stage III/IV PCs." (PMID 33114412, 2020). "Several have been proposed for the detection of PDAC or other cancers in blood, including BCAN, IKZF1, TBX15, BNC1 and SHOX2." (PMID 36434648, 2022).
infection (2 papers, 2016 to 2023). The state of being infected such as from the introduction of a foreign agent such as serum, vaccine, antigenic substance or organism. "In this study, we compared the hypermethyaltion intensity of the BNC1 promoter in HCC tissues with different infection backgrounds." (PMID 26821013, 2016). "As we analyze the TFs that belongs to each time of infection evaluated, we found that at 24-hpi, more than half of TFs are related to an M1 phenotype in humans and mouse, and also were upregulated in our results, corresponding to ARID3A, IRF1, MXD4, and BNC1." (PMID 38162669, 2023).
BNC1 also shares sentences with these, for which no sentence is quoted: ovarian insufficiency (4 papers); renal cell carcinoma (2); colorectal cancer (1); intraductal papillary mucinous neoplasms (1); lung carcinoma (1); lymphocytic leukemia (1); Primary amenorrhea (1); primary ovarian insufficiency (1).